BCL9L (BCL9 like)
Diseases named in the same sentence as BCL9L in open-access papers (continued):
Sharing a sentence is not in itself a finding about the gene and the disease.
pancreatic cancer (6 papers, 2016 to 2021). "This is linked to the induction of a strong epithelial phenotype in pancreatic cancer cells upon BCL9L knockdown even in the presence of the EMT-inducer TGF-β." (PMID 27713160, 2016). "Together, these data consistently suggest that loss of BCL9L induces a subcellular re-distribution of β-catenin with increased retention at the plasma membrane of pancreatic cancer cells." (PMID 27713160, 2016). "Our findings underline the importance of BCL9L for growth and invasion of pancreatic cancer cells and their ability to undergo and complete the EMT process in vitro." (PMID 27713160, 2016). "At this point, we sought to determine whether BCL9L is implicated in growth and metastasis of pancreatic cancer cells in vivo." (PMID 27713160, 2016). "In pancreatic cancer, BCL9L knockdown decreases cell proliferation, migration, invasion, and liver metastasis, and increases E-cadherin expression even in the presence of TGF-β, suggesting a role of BCL9L in regulating EMT31." (PMID 33436545, 2021). "Levels of BCL9L mRNA were determined in tissues from patients with primary pancreatic cancer and chronic pancreatitis using qRT-PCR and compared with expression levels in pancreas tissue from healthy individuals." (PMID 27713160, 2016). "In support of the data obtained in vitro, these results point towards a central importance of BCL9L for growth and liver metastasis of pancreatic cancer cells in vivo." (PMID 27713160, 2016). "A reduction in their expression upon BCL9L knockdown would explain the observed upregulation of E-Cadherin in pancreatic cancer cells." (PMID 27713160, 2016). "Taken together, our findings underline the key importance of BCL9L for EMT and thus progression and metastasis of pancreatic cancer cells." (PMID 27713160, 2016). "Results obtained from xenograft mouse models of pancreatic cancer confirmed the relevance of BCL9L for tumor growth in vivo and showed a highly significant reduction in the number of liver metastases upon BCL9L knockdown." (PMID 27713160, 2016). "In congruence, increased BCL9L protein levels were detected in pancreatic cancer cell lines used for subsequent functional experiments vs a normal human pancreatic cell line (HPNE)." (PMID 27713160, 2016). "This would, however, not explain the clear functional consequences we observed on WNT/β-catenin-dependent cellular processes including reduced migration, proliferation and invasion of pancreatic cancer cells upon BCL9L knockdown." (PMID 27713160, 2016). "In the present study we identify a novel molecular function of BCL9L as a critical modulator of invasion and metastasis of pancreatic cancer cells in vitro and in vivo." (PMID 27713160, 2016). "We demonstrated that the BCL9L specific knockdown induces a strong epithelial phenotype in pancreatic cancer cells even after treatment with the EMT-inducer TGF-β." (PMID 27713160, 2016). "The results obtained so far implicate that BCL9L is involved in the regulation of EMT in pancreatic cancer cells, as its knockdown induced up-regulation of the epithelial marker protein E-cadherin accompanied by increased cell-cell adhesion." (PMID 27713160, 2016). "We employed a TOPFLASH/FOPFLASH luciferase assay to determine to what extent BCL9L is important for β-catenin-/TCF-mediated transcription in pancreatic cancer cells." (PMID 27713160, 2016). "In order to study the functional relevance of BCL9L up-regulation in pancreatic cancer, its expression was stably silenced in Panc-1 cells using two different shRNAs targeting the coding sequence (CDS; shBCL9L_1), and the 3′UTR (shBCL9L_2), respectively." (PMID 27713160, 2016). "RNAi-induced BCL9L knockdown negatively affected proliferation, migration and invasion of pancreatic cancer cells." (PMID 27713160, 2016). "Our data confirm that knockdown of BCL9L leads to an up-regulation of E-cadherin expression with concomitant down-regulation of SNAI2 gene expression in pancreatic cancer cells." (PMID 27713160, 2016).
pancreatic cancer (continued). "Next, we used a BrdU incorporation assay to analyze the effect of stable BCL9L down-regulation on the proliferation of pancreatic cancer cells." (PMID 27713160, 2016). "From these results we conclude that BCL9L expression is decisive for the ability of pancreatic cancer cells to undergo EMT in vitro." (PMID 27713160, 2016). "Image analysis of untreated and BCL9L knockdown cells revealed co-localization of both proteins at the plasma membrane implicating the presence of β-catenin at adherens junctions of pancreatic cancer cells." (PMID 27713160, 2016). "In both studies BCL9L ranked among the top 4% of target genes overexpressed in pancreatic carcinoma." (PMID 27713160, 2016). "Using in vitro as well as in vivo model systems we demonstrate the importance of BCL9L for the progression of pancreatic cancer and propose a novel, so far unknown functional role of BCL9L in the regulation of EMT." (PMID 27713160, 2016). "In summary, we identify BCL9L as a novel regulator of TGF-β-induced EMT in pancreatic cancer." (PMID 27713160, 2016). "It is tempting to speculate that transcriptional regulation of BCL9L expression in response to TGF-β represents another point of crosstalk in pancreatic cancer." (PMID 27713160, 2016). "Finally, xenograft mouse models of pancreatic cancer revealed a highly significant reduction in the number of liver metastases upon BCL9L knockdown." (PMID 27713160, 2016). "Indeed, our data show that down-regulation of BCL9L inhibits induction of EMT by TGF-β in pancreatic cancer cells." (PMID 27713160, 2016). "Importantly, the capacity of BCL9L knockdown cells to form metastases in the liver was almost completely abrogated, which further suggests a central importance of BCL9L during TGF-β induced EMT in pancreatic cancer cells." (PMID 27713160, 2016). "In 42 primary pancreatic tumors the RNA-expression of the FLI1 targets DKK1, INPP5D, IGFBP3 and additionally two members of the Wnt/β-catenin pathway, namely BCL9 and BCL9L, was investigated using quantitative real time PCR." (PMID 27539223, 2016). "Results from further kinetic gene expression analyses revealed that the transcriptional response of pancreatic cancer cells towards TGF-β with down-regulation of E-Cadherin and up-regulation of mesenchymal genes is delayed upon BCL9L depletion." (PMID 27713160, 2016). "In support of a similar situation in pancreatic cancer cells, we did not observe an inhibition of the β-catenin-dependent transcriptional response upon knockdown of BCL9L despite of increased binding of β-catenin to E-cadherin." (PMID 27713160, 2016). "Analysis of a panel of pancreatic cancer cell lines shows a consistently higher expression of BCL9L in comparison to non-cancer cell lines and compared to its homologue BCL9 (data not shown)." (PMID 27713160, 2016). "The results of our study did neither reveal a significant impairment of transcriptional activity nor of nuclear translocation ability of β-catenin in pancreatic cancer cells following knockdown of BCL9L." (PMID 27713160, 2016). "Our data reveal significant over-expression of BCL9L in pancreatic carcinoma tissue samples compared to non-cancer controls." (PMID 27713160, 2016). "Thus, we sought to investigate whether up-regulation of BCL9L expression might fuel EMT and consequently the metastatic spread of pancreatic cancer cells." (PMID 27713160, 2016).
glioma (4 papers, 2021 to 2024). A benign or malignant brain and spinal cord tumor that arises from glial cells (astrocytes, oligodendrocytes, ependymal cells). "Our investigation of the underlying mechanism indicated that higher matrix stiffness increased glioma stemness by activating the BCL9L/Wnt/β-catenin signaling pathway." (PMID 33535177, 2021). "Consistently, BCL9L expression was greater in glioma cells cultured on 16-kPa gels than in those cultured on soft stiffness gels or flask." (PMID 33535177, 2021). "Intriguingly, knocking down BCL9L suppressed the upregulation of CD133 in glioma cells cultured on 16-kPa gels, whereas overexpressing BCL9L further enhanced CD133 expression." (PMID 33535177, 2021). "Integrin-mediated interaction between glioma cells and microenvironment components such as the glycocalyx or BCL9L have also been described and shown to enhance glioma stemness." (PMID 35127517, 2021). "Next, we detected the effects of the matrix stiffness on Wnt/β-catenin signaling downstream of BCL9L in glioma cells." (PMID 33535177, 2021). "Our study further demonstrated that greater matrix stiffness induced Wnt/β-catenin signaling by upregulating BCL9L, ultimately increasing the stemness of glioma cells." (PMID 33535177, 2021). "We performed Western blotting to compare BCL9L levels between HS and LS glioma tissues, and found that BCL9L was upregulated in HS tissues." (PMID 33535177, 2021). "Greater matrix stiffness could obviously up-regulated the expression of BCL9L, thereby promoting the activation of Wnt/β-catenin signaling and ultimately increasing the stemness of glioma cells." (PMID 33535177, 2021). "In addition, silencing BCL9L impaired glioma cell proliferation, whereas overexpressing BCL9L strengthened it, both in vitro and in vivo." (PMID 33535177, 2021). "Our results also suggested that the matrix stiffness and BCL9L levels of glioma tissues could be potential biomarkers for glioma diagnosis or tumor progression analysis." (PMID 33535177, 2021). "We found that a stiffer matrix activated BCL9L and its downstream signals Wnt/β-catenin, whereas inhibiting Wnt/β-catenin signaling improved the anticancer effects of traditional clinical interventions, revealing a potential approach to glioma treatment." (PMID 33535177, 2021).
hepatocellular carcinoma (4 papers, 2020 to 2023). A malignant tumor that arises from hepatocytes. "For example, BCL9L expression is increased in hepatocellular carcinoma (HCC)." (PMID 35628130, 2022). "BCL9L is upregulated in hepatocellular carcinoma (HCC) compared to adjacent non-tumour areas." (PMID 35628130, 2022). "BCL9L overexpression is positively correlated with poor overall survival in hepatocellular carcinoma patients, and silencing BCL9L, but not BCL9, reduced Wnt signaling, and suppressed cell growth and induced apoptosis of Wnt-inactive hepatocellular carcinoma cells." (PMID 33436545, 2021).
intestinal tumor (4 papers, 2014 to 2020). "We have previously characterized the proto-oncogene BCL9-2 (BCL9L, B-Cell Lymphoma 9–like) which augments Wnt/ß-catenin signaling and promotes intestinal tumor progression." (PMID 25149534, 2014). "It was reported that higher expression of BCL9L predict lower survival rates in intestinal tumor patients and could be employed as an independent prognostic biomarker." (PMID 33117820, 2020). "BCL9L (B-cell CLL/lymphoma 9 like) protein shares a conserved domain with BCL9, which is related to intestinal tumor progression." (PMID 30670769, 2019).
B-Cell Lymphoma (3 papers, 2014 to 2022). "Among these genes, we found five genes, ATP5L, BCL9L, CD3G, CXCR5, and DDX6, that have been reported to be associated with the occurrence of B-cell lymphomas, a blood cancer caused by the disorder of immune functional B cells (also known as B lymphocytes) that attack invading pathogens." (PMID 36173765, 2022).
cholangiocarcinoma (3 papers, 2021 to 2024). A carcinoma that arises from the intrahepatic biliary tree (intrahepatic cholangiocarcinoma) or from the junction, or adjacent to the junction, of the right and left hepatic ducts (hilar cholangiocarcinoma). "In digestive system tumors, the LINC00665/miR-186-5p/MAP4K3 axis and the LINC00665/miR-424-5p/BCL9L axis promote the progression of hepatocellular carcinoma and cholangiocarcinoma, respectively." (PMID 35563845, 2022). "In addition, knockdown of LINC00665 also downregulated Wnt/β-Catenin signaling and the expression of nuclear transcriptional regulator BCL9L in cholangiocarcinoma cells treated with gemcitabine." (PMID 35563845, 2022).
osteosarcoma (3 papers, 2020 to 2023). A usually aggressive malignant bone-forming mesenchymal neoplasm, predominantly affecting adolescents and young adults. "In summary, we found the inhibitory effect of miR-766-3p on the occurrence and development of osteosarcoma and its potential mechanism via BCL9L and the β-catenin signal pathways." (PMID 33117820, 2020). "And overexpressing miR-766-3p suppressed proliferation, EMT and metastasis in osteosarcoma by downregulating the expression of BCL9L via the β-catenin/TCF-4 signaling pathway." (PMID 33117820, 2020). "- Upregulated miR-766-3p suppresses migration and invasion of osteosarcoma by targeting BCL9L." (PMID 37205191, 2023). "However, the effects of BCL9L in osteosarcoma has never been clearly reported, and the relationship between the miR-766-3p/BCL9L axis and β-catenin signal pathway involved in OS is still subject to intense investigation." (PMID 33117820, 2020).
triple-negative breast carcinoma (3 papers, 2021 to 2022). An invasive breast carcinoma which is negative for expression of estrogen receptor (ER), progesterone receptor (PR), and human epidermal growth factor receptor 2 (HER2). "The expression of BCL9/BCL9L negatively related to the infiltration of CD8+ T cells in triple negative breast cancer, and BCL9/BCL9L inhibited the infiltration of CD8+ T cells in the tumor microenvironment." (PMID 34579753, 2021). "Hypomethylation within this gene in CLL patients with SF3B1 mutation has been previously reported and it has been recently shown that BCL9 and BCL9L promote tumorigenicity in a triple negative breast cancer mouse model through immune-dependent (TGF-β) and immune-independent (Wnt) pathways." (PMID 34502260, 2021). "In triple-negative breast cancer (TNBC), BCL9L mediates the malignancy of TNBC through Wnt/β-catenin and TGF-β signalling pathways." (PMID 35628130, 2022).
colorectal tumors (2 papers, 2008 to 2020). "Additionally, BCL9L was abnormally elevated in 43% of colorectal tumors, and could enhance the transcriptional activity of tumor cell invasion mediated by β-catenin-TCF." (PMID 33117820, 2020).
leukemia (2 papers, 2016 to 2024). A malignant (clonal) hematologic disorder, involving hematopoietic stem cells and characterized by the presence of primitive or atypical myeloid or lymphoid cells in the bone marrow and the blood. "BCL9 (B-cell CLL/lymphoma 9) and its homologue BCL9L (B-cell CLL/lymphoma 9-like, BCL9-2, DLNB11) have previously been shown to be associated with the formation of leukemia and other human malignancies." (PMID 27713160, 2016).
liver cancer (2 papers, 2020 to 2021). An epithelial or non-epithelial malignant neoplasm that arises from the liver. "Our results confirm Wnt responsiveness of AXIN2, while BCL9 and BCL9L seem not to be Wnt-responsive in liver cancer cells." (PMID 31440992, 2020).
lung carcinoma (2 papers, 2021 to 2022). "The oncogenic role of BCL9L in lung cancers is also supported by the comparison of ∆Np63-regulated enhancers associated genes in AT2 cells and in LUAD derived from tumours of KrasG12D/+ mice, showing that BCL9L is included in the common gene set." (PMID 35105868, 2022). "Finally, to evaluate the relevance of BCL9L as an oncogene in human lung cancers, we analysed its prognostic value in two independent cohorts of LUAD and LUSC." (PMID 35105868, 2022).
acute lymphoblastic leukemia (1 paper, 2020). Leukemia with an acute onset, characterized by the presence of lymphoblasts in the bone marrow and the peripheral blood. "In 11q23.3, rs75438046 maps to the 3′ UTR of CXCR5, which controls viral infection in B cell follicles, and BCL9L, a translocation target in acute lymphoblastic leukemia and transcriptional activator of the Wnt/β-catenin cancer signaling pathway." (PMID 33109261, 2020).
alcohol abuse (1 paper, 2020). The use of alcoholic beverages to excess, either on individual occasions ("binge drinking") or as a regular practice. "While expression of BCL9 seemed to be independent of tumor etiology, BCL9L levels were lowest in patients with alcohol abuse and hepatitis B infections." (PMID 31440992, 2020).
chronic pancreatitis (1 paper, 2016). A chronic inflammatory process causing damage and fibrosis of the pancreatic parenchyma. "BCL9L gene expression was detected in 80% of PDAC cases and significantly elevated compared to chronic pancreatitis and healthy pancreas tissues." (PMID 27713160, 2016). "Quantification of mRNA expression levels shows that BCL9L expression is significantly up-regulated in patient-derived PDAC tissues compared to tissues derived from non-cancer and chronic pancreatitis patients." (PMID 27713160, 2016).
gastric cancer (1 paper, 2021). A primary or metastatic malignant neoplasm involving the stomach. "Next, we further examined the association between BCL9L and drugs resistance in gastric cancer." (PMID 34319913, 2021). "More importantly, suppression of BCL9L by sh RNA also suppressed the up-regulation of β-catenin in collagen cultured ITGB1 positive cells, indicating that BCL9L mediated the activation of β-catenin signals in gastric cancer." (PMID 34319913, 2021). "Since Wnt/β-catenin served as the downstream signal of BCL9, we supposed that ITGB1 might upregulate BCL9L to mediate the activation of pro-survival β-catenin signals in gastric cancer." (PMID 34319913, 2021). "Previous reports have implicated the role of BCL9 in tumor development and our study further disclosed the pro-tumor effects of BCL9 paralog BCL9L, which could promote the β-catenin signals activation in gastric cancer." (PMID 34319913, 2021). "Mechanistically, we demonstrated that type I collagen was capable of promoting the activation of BCL9L/β-catenin signaling pathway through ITGB1, thereby contributing to the gastric cancer development." (PMID 34319913, 2021).
melanoma (1 paper, 2021). A malignant, usually aggressive tumor composed of atypical, neoplastic melanocytes. "Further screening of BCL9L in 16 patients with melanoma showed that BCL9L was highly expressed in melanoma tissues and tumor BCL9L levels was positively correlated with the stage of melanoma." (PMID 33274785, 2021). "Indeed, we confirmed that the expression of BCL9L was remarkably upregulated in soft breast (4T1 and MCF‐7) and melanoma (B16 and MP‐1) tumor cells, as evidenced by qPCR, Western blot, and immunostaining (and EV5A and B)." (PMID 33274785, 2021).
metastatic disease (1 paper, 2022). "Considering that Cal29 originates from a muscle-invasive metastatic bladder carcinoma and T24 from a non-muscle invasive and non-metastatic disease, it can be hypothesised that BCL9L/β-catenin signalling plays a crucial role later in the progression of BC." (PMID 35628130, 2022).
non-small cell lung carcinoma (1 paper, 2022). A group of at least three distinct histological types of lung cancer, including non-small cell squamous cell carcinoma, adenocarcinoma, and large cell carcinoma. "We now show that BCL9L is regulated by ΔNp63 and acts as a crucial unifying oncogene in non-small cell lung cancers as well." (PMID 35105868, 2022).
ovarian carcinoma (1 paper, 2016). A malignant neoplasm originating from the surface ovarian epithelium. "In this report, we found that NGF/NGFRs and β-catenin were coexpression in ovarian cancer cell lines, and NGF can decrease the expression level of β-catenin and affect its activities, which may be related to the NGF-induced down-regulation of B-cell CLL/lymphoma 9-like (BCL9L, BCL9-2)." (PMID 27835587, 2016).
pancreas neoplasias (1 paper, 2016). "In contrast, high expression of the gene was detected in PDAC supporting the connection between BCL9L expression and tumor malignancy in pancreas neoplasias." (PMID 27539223, 2016).